AR (androgen receptor)
Diseases named in the same sentence as AR in open-access papers (continued):
Sharing a sentence is not in itself a finding about the gene and the disease.
tumor (continued). "In order to separate healthy from tumor samples in the AR– group, several discriminant function analyses with a leave-one-out cross-validation were carried out, including different sets of biomarkers, not including AR mutation." (PMID 35053623, 2022). "On the other hand, AR acts as tumor suppressor in ER+BCa with high AR levels (BT474, T47D and ZR75.1)." (PMID 35568821, 2022). "In contrast, a study in 2015 found that the mRNA expression level of AR was significantly higher in patients with pT2 tumours than in those with pT1 tumours." (PMID 35452181, 2022). "By demethylating H3K9me3, a repressive mark enriched in heterochromatin, KDM4A–KDM4C function to coactivate AR in the case of PCa, releasing the transcriptional block and promoting tumor progression." (PMID 35534851, 2022). "More specifically, AR causes increased tumor growth in TNBC with high AR levels (MDA-MB-453) and in ER+BCa with low AR levels (MCF7)." (PMID 35568821, 2022). "In our trial, CR1447 failed to attain the primary endpoint for several different reasons, such as aggressive tumor type in the third-line setting and patient selection based on a low AR expression of >0%." (PMID 37435469, 2022). "Mechanistic studies in TNBC cell lines provide evidence that the AR interacts with AREs and stimulates tumor cell proliferation in an androgen-dependent manner." (PMID 36139643, 2022). "Expression of Androgen receptor was more among women with TNBC in the age range of 51 to 60 years at 35.3%, among patients having tumour sizes<5-cm confirming that as tumour mass increased, the expression of androgen receptor decreased." (PMID 35463732, 2022). "This indicates that to better recapitulate the processes leading to castration resistance, AR-ChIP for ARBS profiling should be performed using in vivo tumor tissues." (PMID 35365763, 2022). "Previous studies have shown that lack or low levels of nuclear AR in stromal cells (sAR(-)), adjacent to tumor cells, are observed in the context of high Gleason scores, and metastasis." (PMID 36115838, 2022). "Transcriptome sequencing of tumor lesions from the same patient after neoadjuvant hormonal therapy (NHT) revealed that NHT treatment significantly inhibited AR pathway activities in adenocarcinoma, but had less effects on AR signaling activities in IDC-P." (PMID 36591521, 2022). "Both GR and AR have similar structures and mechanisms of action; thus, in mCRPC, whenever a treatment is used to block AR signaling, GR is usually activated to attach to nuclear AREs and activate genes that stimulate tumor progression and cell endurance." (PMID 36176747, 2022). "The implications for a role of AR in DDR make it an interesting target for combination therapeutics with RT, as AR inhibition should potentiate radiation-induced damage in a tumour-selective manner." (PMID 36376977, 2022). "We focused on adeno-NEPC with dual expression of neuroendocrine markers and AR in the same tumor samples resulting from tumor heterogeneity." (PMID 36572885, 2022). "CCS1477, a new selective inhibitor of the p300/CBP bromodomain, blocks AR and AR-Vs signaling in the cell line, patient-derive xenografts, and in serial tumor biopsies from an ongoing phase I clinical trial." (PMID 36551557, 2022). "Data showed that OCM ABI did not affect PC-3 cell proliferation suggesting that the indirect anti-tumor effect of ABI was AR-mediated." (PMID 36140255, 2022). "While prior studies focused on concordance between patient subgroups, inter-tumor heterogeneity of AR enhancer selectivity remains unexplored." (PMID 36450752, 2022). "Tumor mass and AR expression will regress temporarily after ADT treatment; however, most patients will eventually develop castration-resistant prostate cancer (CRPC) and re-acquire high levels of AR and PSA." (PMID 35841025, 2022).
tumor (continued). "In contrast, reduced expression of AR in CAFs, often in response to androgen/AR-pathway directed therapies, appears to promote tumor growth and progression, correlating with a high Gleason score, disease recurrence, and shorter progression-free survival." (PMID 36671452, 2022). "Despite the initial response, the tumor develops resistance against these otherwise promising drugs by eventually reinstating AR signaling with the intra-tumoral levels of androgens close to that found in the normal prostate gland." (PMID 36078112, 2022). "Among others, AR has been considered as a marker of indolent RCC and is associated with tumor-suppressive activity." (PMID 36552000, 2022). "FOXA1 induces tumor cell proliferation by activating the AR pathway but downregulates IL-8 by binding to its promoter and inhibiting EMT." (PMID 35938167, 2022). "AR is relevant in tumor development, and it was shown that AR binds to the promoter region of mIR-26a-5p, suppressing its expression and antitumor activity." (PMID 35327549, 2022). "The heatmap demonstrated that tumours with a higher ZFHX3 level also had a higher AR activity (left)." (PMID 34953044, 2022). "In fact, the AR agonist activation altered the genomic distribution of ER and essential co-activators (p300, SRC-3), resulting in repression of ER-regulated cell cycle genes and upregulation of AR target genes, including known tumor suppressors." (PMID 36111296, 2022). "Because BAT eventually leads to resistance, the authors tested cycling between SPA and AR antagonism in a patient-derived xenograft and observed a delay in tumor growth." (PMID 36453547, 2022). "AR-AF regulates the proliferation, apoptosis, migration and angiogenesis of tumor cells by regulating THE cAMP signaling pathway, and PI3K-Akt signaling pathway." (PMID 35672352, 2022). "PCa tumours are dependent on steroid hormones such as testosterone, which is derived from cholesterol, through AR activation." (PMID 35215499, 2022). "We first sought to characterize the intrinsic effects of these tumor-derived, hypoxia-stimulated cytokines, specifically their contribution to sustained AR pathway activity under hypoxic conditions in vitro." (PMID 35302608, 2022). "Selective GR modulators inhibited GR transcriptional activity and decreased GR-mediated tumor cell viability post-AR blockade." (PMID 36291899, 2022). "KDM4A serves as a coactivator of E2F1 and KDM4B regulates AR signaling and turnover to promote tumor progression." (PMID 35534851, 2022). "Transcriptional factor regulatory network analysis showed that the miR-657 target WT1 (Wilms’ tumour gene) and the miR-582-5p target ETV1 (ETS variant 1) regulate the AR gene at the same time." (PMID 35163477, 2022). "In this regard, it is important to understand the relationship between distinctive metabolic features, AR signaling, genetic drivers in PCa, and the tumor microenvironment (TME) to identify metabolic vulnerabilities." (PMID 36358940, 2022). "The study confirmed that AR competes with ER to bind cofactors and responsive elements in chromatin and block ER–mediated tumor proliferative effects." (PMID 36556209, 2022). "Testosterone ablation by castration impaired the tumor-suppressor function of Foxp1 and revealed Foxp1 as a negative regulator of AR-driven proliferation in the prostatic tissues." (PMID 36139541, 2022). "Initially, ADT typically leads to 90-95% decrease in circulating androgen levels, being complemented by a 50% decrease in intraprostatic dihydrotestosterone (DHT) and AR inhibition, impairing tumor cells’ survival." (PMID 35686097, 2022). "To further confirm these findings, we focused on the AR locus, for which numerous inter-tumor heterogeneous ARBS loop to the TSS and with confirmed AR binding and transcriptional activity in our primary patient cohort." (PMID 36450752, 2022).
tumor (continued). "Expression of androgen receptor (AR) was analyzed in many tumors supplying information about tumor growth, survival time and advancement for antiandrogen therapy." (PMID 36552000, 2022). "The tumor xenografts from AR-overexpressing 22Rv1 were larger in volume and heavier in final weight than the empty vector-transfected 22Rv1 xenografts." (PMID 36078112, 2022). "Understanding resistance mechanisms, including the role of AR expressed in other cell types within the tumor microenvironment, will extend the clinical benefit of AR-targeted therapy." (PMID 35302608, 2022). "Baseline high circulating tumor DNA (ctDNA) fraction in plasma and androgen receptor (AR) copy number (CN) gain correlates with worse outcomes." (PMID 35565349, 2022). "Elevated serum concentrations of the AR downstream target prostate-specific antigen (PSA) are evidence in support of this AR-mediated tumor growth." (PMID 35669435, 2022). "Abiraterone, an androgen synthesis inhibitor with antiandrogen properties, targets the AR by further suppression of available androgens in the tumor microenvironment and has demonstrated clinical benefit in both CRPC and HSPC." (PMID 35769712, 2022). "16β-[18F]fluoro-5α-dihydrotestosterone ([18F]FDHT) PET/CT was developed to assess the AR status in tumor lesions and showed a good correlation between tracer uptake and AR expression in biopsied tissues in several studies." (PMID 35565232, 2022). "In GBM, upregulation of the AR gene can alter DNA repair responses, immunity, and the hormone status in the tumor microenvironment." (PMID 36013056, 2022). "We can infer that the emerging themes such as “androgen receptor expression”, “growth-factor receptor”, “neoadjuvant chemotherapy”, and “tumor-infiltrating lymphocyte” need further investigation." (PMID 35800434, 2022). "Recently, the androgen receptor (AR) has been identified as a tumor suppressor in ER-positive BRCA; however, the relationship between the levels of androgens and ICRs on T cells in BRCA is unclear." (PMID 35880165, 2022). "Upon castration, AR activity and tumor growth are suppressed (POST-CX), however, this initial responsiveness to castration reproducibly gives way to castration-resistance (CRPC)." (PMID 36167836, 2022). "Elevated serum concentrations of the AR downstream target prostate specific antigen (PSA) are indicative of this AR-mediated tumor growth." (PMID 35109899, 2022). "Trials have demonstrated strong efficacy of this drug in improving time to progression and extending overall survival in patients whose tumor is AR responsive." (PMID 35681683, 2022). "Another reported tumor suppressor is the miR-488, which negatively regulates the transcriptional activity of AR, blocking proliferation and increasing apoptosis in CaP cells." (PMID 35456428, 2022). "Previous reports have shown that advanced PCa cells can switch from AR signalling to ERα signalling in response to ADT to maintain tumour cell proliferation under androgen-deprived conditions." (PMID 36376959, 2022). "In metastases, AR staining was pronounced in the nucleus of metastatic tumor epithelial cells, whereas most cells in the metastasis stroma were AR negative." (PMID 36358614, 2022). "Others such as LCoR (ligand dependent corepressor), inhibit AR-mediated transcription by interacting with HDACs and CtBP (C-terminal binding protein), which suppress tumor growth in vivo." (PMID 35269520, 2022). "Altogether, these data demonstrate a promotional role of stromal AR signaling in Gli1-expressing cells to support prostate epithelial oncogenesis and tumor initiation." (PMID 36323713, 2022). "Androgen receptor (AR) pathway inhibitors are among the clinically commonly applied drugs for the population with PC, exerting potent tumor-killing effects." (PMID 35551634, 2022).
tumor (continued). "The finding that CAFs harbor significant amounts of AR has opened new ways for a better understanding of the role of tumor microenvironment in PC progression and more tailored approaches of this cancer." (PMID 35222290, 2022). "In GCNIS-containing tubules, from biopsies located ‘adjacent’ to the tumour and ‘distant’ to the tumour, Sertoli cells co-expressing cytokeratin and AR were quantified." (PMID 36428571, 2022). "The inhibition of FASN in different castration resistant cell lines decreased tumor growth, increased apoptosis, altered the lipidome, decreased lipid accumulation, and decreased the expression of the AR and AR-V7." (PMID 36077824, 2022). "Though both agents delayed tumor growth, AR-ASOs were more effective than enzalutamide in both preclinical models." (PMID 35650195, 2022). "AR can function as both a tumor suppressor and a proliferation stimulator during PCa progression, and AR-downregulated genes can either be involved in tumor suppression or tumor progression." (PMID 36293081, 2022). "A recent report showed that T cell intrinsic AR activity represses the IFNγ expression from T cell exhaustion and that AR blockade can directly enhance CD8 T cell functions in order to sensitize the tumor bearing host to an immune checkpoint blockade." (PMID 36430730, 2022). "During the administration period, the tumor growth rate in nude mice was slow, and tumor reduction was observed in the Di-PP/AR-siRNA/DTX group." (PMID 35631549, 2022). "Proliferation of tumor cells is generally thought to be increased by AR with evidence of cell-cycle regulation downstream of various androgen-responsive transcriptional activities." (PMID 35203574, 2022). "The in vivo activity of 2-75 was accompanied by increased apoptosis induction and suppressed AR nuclear accumulation in the tumor bodies of treated mice." (PMID 35582529, 2022). "Emerging data show that AR’s role in BC is dependent on several factors including, but not limited to, disease subtype, tumour microenvironment, and levels of circulating oestrogens and androgens." (PMID 36376977, 2022). "In all patients (women and men), AR protein expression was higher in the enhancing tumor region and in the peritumoral area than in the tumor core." (PMID 36361793, 2022). "Here we show that changes in chondroitin sulfate (CS), a major glycosaminoglycan component of the tumor cell glycocalyx and extracellular matrix, is AR-regulated and promotes the adaptive progression of castration-resistant prostate cancer (CRPC) after ARPI." (PMID 35963852, 2022). "These recent scientific acquisitions are creating the basis to widen the treatment scenario of this tumor, evolving from targeting the androgen receptor axis or the traditional chemotherapy approach." (PMID 35205654, 2022). "We translated the CRPC AR-V+ phenotype in our tumor model to LNCaP cells expressing AR-V7, while androgen-resistant LNCaP cells overexpressing AR-FL mimicked the reference cohort (CRPC)." (PMID 36139600, 2022). "The result of tumor immune infiltration showed that AR was positively correlated with CD4+ T cells, macrophages, and dendritic cells, while ERBB2 was negatively correlated with CD8+ T cells, macrophages, neutrophils, and dendritic cells." (PMID 35069767, 2022). "GABPA is a downstream target of the androgen receptor in PCa and enables the tumor cells to become more aggressive." (PMID 34879849, 2021). "ERG together with co-repressors, like HDACs and EZH2, modulates AR transcriptional activity, impeding epithelial differentiation and contributing to tumor progression." (PMID 34230470, 2021). "With the research on chemical constituents of AR in recent years, the study of its anti-tumor effect has become a hot spot in recent years." (PMID 34887934, 2021).
tumor (continued). "AR-tropomyosin receptor kinase (TRK) crosstalk mediated through nerve growth factor (NGF) also promoted tumor growth in ARSI challenged PCa cell lines, and are targetable by NTRK1/TRKA inhibitors." (PMID 34771580, 2021). "The purpose of the study was to find out if it is a concordance between flour-dihydro-testosterone and 8F-fluoroestradiol PET and tumor AR and ER expression measured by immunohistochemistry." (PMID 33802610, 2021). "Drugs such as enzalutamide demonstrated that the improvement in anti-tumour efficacy is closely correlated with an affinity for the AR and its activity and have established the paradigm that AR remains activity in aggressive disease." (PMID 33993099, 2021). "Direct blockade of AR would probably be more effective however, considering the potential for intra-tumor steroidogenesis." (PMID 34063736, 2021). "AR also plays a role in anchorage-independent cell survival and cancer stem cell-like characteristics including tumor initiation in-vivo." (PMID 34736512, 2021). "Histology of the VCaP-Enza-B tumours and expression of the AR and cell cycle marker Ki67 were subsequently investigated by immunohistochemistry." (PMID 34749299, 2021). "Bromodomain and extra-terminal chromatin readers (BET) inhibitors including miverbresib and ZEN-3694 regulate AR gene transcription to decrease AR expression and AR-V7 signaling, which results in tumor suppression." (PMID 34771580, 2021). "AZD3514 is another SARD shown to be effective in preclinical studies at inhibiting receptor signalling and reducing tumour burden in xenograft models by targeting the AR for degradation." (PMID 33572755, 2021). "It was postulated that the tumor clones with high AR amplification were localized to sites of bony metastasis." (PMID 34771580, 2021). "Despite the AR downregulation in LNCaP cells after bacteriophage exposure, tumor cell viability was only transiently compromised after 4 and 24 h of treatment for T4 and M13 phages, respectively." (PMID 34578333, 2021). "Here, molecular mechanisms are described that review knowledge about tumor cells escape therapy by developing bypass mechanisms of AR-signaling." (PMID 33810413, 2021). "In some tumors like PCa, upregulation and the interplay between MYC, AR, and the mTOR mutations cause Gln addiction when Gln becomes a conditional EAA for tumor growth and survival." (PMID 33401748, 2021). "Androgen receptor (AR) exhibited lower expression (~−5×) in the LNCaP xenograft tumor compared to cultured cells (p < 0.05)." (PMID 33808801, 2021). "ADT aims to inhibit tumour growth by preventing the activation of a nuclear transcription factor, the androgen receptor (AR)." (PMID 34434533, 2021). "Classical chemotherapies for PCa include AR-targeted drugs that block the activation of AR and taxane chemicals that inhibit tumor cell proliferation or induce tumor cell apoptosis." (PMID 33506020, 2021). "Clinical evidence indicated that stromal AR was a protective factor for PCa patients as its expression was inversely related to poor PCa outcomes including tumor stage, metastasis, cancer relapse, and cancer-related death." (PMID 34692685, 2021). "In ETA, targeted agents were selected based on NGS findings (SNV, CNA and Differential Gene Expression, DGE), endocrine agents were selected on the basis of hormone receptor (ER/AR) expression as determined by immunohistochemistry (IHC) on tumor tissue." (PMID 33935721, 2021). "This indicates LINC00667 functions as a tumor promotor in promoting HCC progression through targeting miR-130a-3p/AR axis, making a novel biomarker and potential therapeutic target for HCC." (PMID 34907204, 2021). "Recent studies revealed the clinical significance of bromodomain and extra-terminal (BET) domain proteins, which are known transcriptional coactivators of tumor-promoting genes such as AR and are considered as a potential therapeutic target for CRPC treatment." (PMID 34493733, 2021).